CD44 (CD44 molecule (IN blood group))
Diseases named in the same sentence as CD44 in open-access papers (continued):
Sharing a sentence is not in itself a finding about the gene and the disease.
breast carcinoma (continued). "Targeted drug delivery systems using nanocarriers offer a versatile platform for breast cancer treatment; however, a robust, CD44-targeted niosomal formulation has not been developed and deeply studied (both in vitro and in vivo) yet." (PMID 35875198, 2022). "Besides this, it has been reported that HAS2 knockdown in breast cancer cells leads to a downregulation of HYAL2 and CD44." (PMID 35767191, 2022). "These cubosomes wereefficiently taken up by two CD44-expressing cancer cell lines (MDA-MB-231and HT29, representing breast and colon cancer) but not by two CD44-negativecell lines (MCF-7 breast cancer and HEK-293 kidney cells)." (PMID 35938983, 2022). "However, an article in 2003 demonstrated that CD44 and CD24 are viable cell surface markers for identifying breast cancer stem cells by in vivo xenograft formation of serially diluted xenograft tumor cells derived from multiple passaging in mice." (PMID 35883497, 2022). "However, a recent study reported that CD44 knockdown promoted the proliferation and migration of claudin‐low MDA‐MB‐231 and Hs 578T breast cancer cell lines." (PMID 35229451, 2022). "In breast cancer, BCSCs were initially identified as the CD24−/CD44+ phenotype." (PMID 36230903, 2022). "In the current model, atropine reduced EMT in both the chemo-resistant, triple-negative, claudin-low mesenchymal-like breast cancer (MDA-MB-231) cell line and the luminal A epithelial-like cell line (T47D) through the upregulation of the level of E-cad and the reduction of both CD-44 and c-Myc." (PMID 36077256, 2022). "Some studies showed that estrogen treatment increases BCSC properties, including mammosphere forming efficiency and the proportion of CD44+/CD24− cells, in ER+ breast cancer cell lines and that this effect was reversed by endocrine therapy, suggesting that ER is necessary for stem cell expansion." (PMID 36482488, 2022). "In addition, the downregulation of FoxO3 leads to changes in the levels of CD44/CD24, which are breast cancer stem cell markers." (PMID 36142156, 2022). "Considering the effects sHA of on the breast cancer cells’ functional properties, the correlation between these changes and modulations to the expression of HA partners, such as HA synthases (HAS2 and -3) and CD44, was investigated." (PMID 34944559, 2021). "In addition, the results indicate that activation of LIFR signaling in breast cancer cells in the existence of CAF-secreted LIF can induce Nanog and Oct4 expression and increase breast cancer stem cell markers CD24−/CD44+." (PMID 34947829, 2021). "We accessed GSE7513 and GSE52327, which consist of gene array data from breast cancer patient tumor cells sorted for CD44+/CD24- or ALDH+ from cells lacking these marker profiles." (PMID 35127497, 2021). "Interestingly, CD44 interacts with the Na+/H+ exchanger NHE1 and participates in acidification-induced EMT in breast cancer cells." (PMID 34680442, 2021). "To assess whether CD44 is degraded by MARCH8 and/or contributes to the phenotype of MARCH8 in breast cancer cells, we performed immunoblotting, immunofluorescence (IF) staining, and flow cytometry analysis of CD44 in MARCH8-expressing cells." (PMID 34067416, 2021). "Additionally, HMMR also interacted with CD44, another HA receptor characterized by forming complexes with ERK1/2, to exert its functions in breast cancer." (PMID 35036134, 2021). "In addition, lnc408 expression was positively correlated with the protein level of stemness marker (e.g., CD44 and SOX2) in both breast cancer cells and clinical samples." (PMID 33934099, 2021).
breast carcinoma (continued). "Following treatment with PFD, we found that PFD significantly reduced the migration of an invasive type of breast cancer cells and CAFs, and significantly decreased the expression of EMT marker vimentin, stemness marker CD44, and YAP1 in CAF-tumor spheroids at the protein level." (PMID 34680267, 2021). "The mechanisms of chemo-resistance in breast cancer include ATP-binding cassette (ABC) transporters such as P-gp transporting a variety of drugs outside the cell membrane, and formation of cancer stem cells (CSCs) which carry CD44." (PMID 33413403, 2021). "Moreover, TET3 knocked-down cells under normoxia exhibited an identical alternative splicing pattern of ESRP1 targets (hMENA, SLK, SCRIB, RALGPS2, SLC37A2, FNIP1, CD44, and ARHGEF1) as the hypoxic breast cancer cells." (PMID 34362878, 2021). "Notably, the PDE5 gene was inversely associated with multiple metastasis suppressor genes (MSGs) (ARHGDIB, BRMS1, CASP8, CD44, CDH2, MAP2K4, MAPK14, PEBP1) in three human breast cancer gene expression cohorts (GSE2034, GSE1456 and GSE26304)." (PMID 35008687, 2021). "In breast cancer cell lines MDA-MB-468 and MCF-7, the IL-6/STA3 pathway plays a crucial role in EMT by upregulating TGF-β, a multifactorial cytokine that is again a target of RFX1 and a downstream signaling molecule of CD44 in breast cancer cells." (PMID 33964962, 2021). "Therefore, elemene was found to reduce the CD44+ CD24−/low cell ratio and reverse breast cancer resistance to Adriamycin by reducing the serum pellet-free rate of MCF-7/ADM cells and the expression of BCRP and P-gp genes/proteins." (PMID 34641334, 2021). "In addition, we found HMGA2 knockdown increased CD24+ CD44+ breast cancer in moderate HMGA2 expressed cell line and increased CD24+ CD44- in HMGA2 overexpressed cell lines." (PMID 34680349, 2021). "Furthermore, 72 h treatment with PF-06424439 alone decreased the transcript levels of CD44 and CD166, two CSC markers commonly expressed among primary breast carcinomas, compared with untreated cells." (PMID 34576263, 2021). "We sorted CD44+CD24−/low cells (BCSCs) and CD44+CD24+ cells (non-BCSCs) from MCF-7ADR breast cancer cells by fluorescence-activated cell sorting." (PMID 34403222, 2021). "Cufi and colleagues were the first to demonstrate a link between autophagy and the maintenance of tumours, whereby autophagy promoted higher expression levels of CD44 and vimentin in BCSCs (CD44+CD24-/low cells) isolated from the JIMT-1 epithelial breast cancer cell line." (PMID 33799834, 2021). "Indeed, breast TICs possess a mesenchymal gene expression signature supportive of mesenchymal and stem-like properties observed in breast cancer cells undergoing EMT such as elevated expression of ALDH and CD44 and low expression of CD249,11,29." (PMID 33772015, 2021). "Moreover, both Ber and C60-Ber nanocomplex treatment significantly decreased expression of adaptor protein Ruk/CIN85, which was found to modulate CD44 and CD24 expression levels and to be involved in the maintenance of CSC features in breast cancer cells." (PMID 34683705, 2021). "CD44 and CD74 were expressed on most CTCs and their expression was strongly correlated, whereas matched breast cancer BM tissues were much less frequently expressing CD44 and CD74 (negative in 46% and 54%, respectively)." (PMID 34209696, 2021). "Excised xenografts were assessed histologically by H&E staining and immunohistochemistry for breast cancer marker (ERB1), proliferation marker (Ki67), mitotic marker (pHH3), hypoxia marker (HIF-2α), CSC markers (CD47, CD44, CD24, and CD133), and vascularization markers (CD31, CD34)." (PMID 34205080, 2021). "Studies have shown that CD44+/CD24− and ALDH1+ breast cancer stem cells are enriched in TNBC and may contribute to the propensity of TNBC for chemoresistance and tumor metastasis." (PMID 34944829, 2021).
breast carcinoma (continued). "(A) Immunofluorescent analysis of the percentages of CD44-/CD24- cells in tissue samples from breast cancer patients with or without tumor metastasis." (PMID 34318746, 2021). "A possible role of miRNAs in the determination of breast cancer stem cells has been suggested through the demonstration of differential expression of miRNAs in CD44+/CD24-/low breast cancer stem cells versus non-tumorigenic cancer cells." (PMID 34804971, 2021). "However, the interaction of CD44 with HMW–HA and RHAMM can also result in expression of genes such as MMP9 that are utilized for both cutaneous wound repair and breast cancer progression." (PMID 34827550, 2021). "The major characteristic of CSCs in breast cancer is that they express high CD44 levels and low/none CD24 levels and thus are identified as CD44high/CD24low/-cells." (PMID 34072893, 2021). "Given that CSCs are crucial for breast cancer progression and metastasis, RHBDL2 may be a new therapeutic target for control of CD44-/CD24- cell conversion into CSCs to reduce CSC pool size and limit breast cancer progression and metastasis." (PMID 34318746, 2021). "Breast cancer patient P6, a HER2 and hormone receptor-positive breast cancer patient (HER2+, ER+, PR+), with additional metastases in bone, lung and liver, had 16 detectable CTCs, all with a strong or intermediate expression of both CD74 and CD44." (PMID 34209696, 2021). "BCSCs with CD44+/CD24−/low and ALDH1 phenotypes isolated from different subtypes of breast cancer, based on molecular profiling of receptor expression (estrogen receptor, progesterone receptor, or human epidermal growth factor receptor 2), have similar gene expression profiles." (PMID 33925129, 2021). "In contrast, knocking down hRNase 1 by small hairpin RNA (shRNA; sh-R1#1 and sh-R1#2) in KPL4 HER2+ breast cancer cells which express high levels of hRNase 1 significantly reduced the sphere-forming ability, the population of CD24−/CD44+ cells, and the TIC frequency." (PMID 33986289, 2021). "Furthermore, breast cancer cells MCF7 (CD24+/CD44−) and MDA-MB-231 (CD24−/CD44+) were continuously exposed to exogenous LIF and analyzed for CD24/CD44 expression variations over time." (PMID 34947829, 2021). "We have established five breast cancer PDXs with various molecular subtypes including luminal A and B, triple-negative breast cancer, and identified ALDH as a BCSC marker for BC0244, BC0634, BC0350, VBC108, and CD44+CD24− as BCSC marker for BC0145 PDXs." (PMID 35046949, 2021). "Single-cell RNA-Seq analysis conducted with breast cancer CSCs showed a population with hybrid EMT and CSC markers CD44, ABCG2, and ALDH1A1/3, which might mark the MICs." (PMID 34150761, 2021). "Moreover, the mRNA and protein levels of representative breast cancer stemness markers, including SOX2, Nanog, and CD44 were notably decreased in the lnc408-knocked down cells compared to their scrambled control cells (sh Ctrl)." (PMID 33934099, 2021). "CD47 overexpression has been reported to enhance the CD44+/CD24− population in breast cancer, but not sufficiently to increase its stemness." (PMID 34205080, 2021). "Given that CD44+/CD24− is the phenotype of breast CSCs, Nrf2 levels could also be a prognostic marker in breast cancer." (PMID 34770867, 2021). "The CD44 signalling pathway can upregulate MMP-14 expression in basal-like breast cancers, whereby this upregulation correlates with the induction of basal-like breast cancer cells invasiveness." (PMID 34944493, 2021). "A study in breast cancers revealed that EMT promotes stemness in breast cancer cells by gaining cancer stem cell properties, including the ability to self-renew and tumorigenicity, and exhibiting a CD44+/CD24−/low phenotype." (PMID 34217266, 2021). "Moreover, following 4, 6, and 10 days of CAF-CM exposure of breast cancer cells, the expression of CD24/CD44 cell surface markers was analyzed by flow cytometry." (PMID 34947829, 2021).
breast carcinoma (continued). "In addition, the TF, RUNX2, can promote CD44/CD24 breast cancer stem cell properties and breast cancer tumorigenesis through the EMT process." (PMID 34993131, 2021). "CD44 also participates in the switch on different pathways (AKT, STAT3, β-catenin, among others) that activate, as a final event, different mesenchymal markers promoting invasion and metastasis in breast cancer cells." (PMID 33506060, 2021). "In the case of breast cancer stem cells (BCSCs), Al-Hajj and colleagues prospectively isolated a tumorigenic population of cells from primary human breast cancer using FACs based on the ESA+/CD44+/CD24−/low/lineage− phenotype." (PMID 33572626, 2021). "A different study reported that an amplified expression of CD44+/CD24− and aldehyde dehydrogenase 1 (ALDH1) in breast cancer cell line conferred stemness; which induced anoikis resistance through an increase in the phosphorylation of signal transducers and activators of transcription 3 (STAT3)." (PMID 33854965, 2021). "Altogether, these results indicate that Sdc-1 depletion has a negative impact on the CSC phenotype of both breast cancer cell lines, as we observed a reduction in CD44 expression in MDA-MB-231 cells." (PMID 34070901, 2021). "Therefore, we tested the impact of the exogenous LIF, and it altered the morphology of breast cancer cells to a cancer stem-cell-like phenotype, which was explained by the enhanced expression levels of dedifferentiation markers CD24−/CD44+." (PMID 34947829, 2021). "In breast cancer, different subsets of CSCs were identified based on ALDH1, CD44, and CD24; and the two subpopulations (epithelial-like ALDH1+, mesenchymal like CD44+/CD24–) were shown to be capable of inter converting among themselves as well as give rise to non-CSCs." (PMID 32426371, 2020). "Approaches with the knockdown of GRP78 helped to elucidate that this chaperone is required for the self-renewal ability and radioresistance in CSC-like cell fractions from breast cancer MCF-7 cells and also for chemo- and radioresistance in CD24(−)/CD44(+) stem cells of head and neck cancer." (PMID 32268506, 2020). "Analysis of nonluminal breast cancer tissue samples before NAC showed that the mRNA expressions of CD44 and N-cadherin in the NMHR group were higher than that of the MHR group." (PMID 33282946, 2020). "In solid tumors, CSCs are identified by specific markers or marker combinations (e.g., CD44 and CD24 in breast cancer; CD133, CD166 and aldehyde dehydrogenase in colorectal cancer; CD133, CD44, aldehyde dehydrogenase and epithelial cell adhesion molecule in pancreatic cancer)." (PMID 32824649, 2020). "High Col-I density increased CD44+CD24− breast cancer stem cell (BCSC) immunophenotype but failed to potentiate Col-I fiber alignment, cell self-renewal and clonogenicity in MDA-MB-231 cells." (PMID 32435546, 2020). "Identified early in this century, breast cancer stem-like cells (BCSCs) were originally characterized by high expression of CD44 and low or negative expression of CD245." (PMID 32427938, 2020). "In agreement, tissues from breast cancer patients of triple-negative breast cancer (TNBC), the most aggressive form of breast cancer, showed CD44+, CD24–, and high ALDH1 phenotype compared to the nonTNBC tissues." (PMID 32391048, 2020). "In this study, we demonstrated that the breast cancer stem-like cells, MCF-7/SC, possess prominent stem cell properties such as an enhanced CD44+/CD24− population, reduced ROS levels, and increased mammosphere formation ability compared with the parental MCF-7 cells." (PMID 32503225, 2020). "Before NAC, the nonluminal breast cancer with poor response to chemotherapy showed relatively low expression of E-cadherin and β-catenin and relatively high expression of CD44 and N-cadherin compared to the MHR group." (PMID 33282946, 2020).
breast carcinoma (continued). "In CD44+/CD24neg/low and CD44+/CD24+ tumorigenic cell populations derived from basal-like breast cancer cells, non-cytotoxic concentrations of metformin (1 mM) suppressed the occurrence of stem-cell-like characteristics by the suppression of EMT." (PMID 32883003, 2020). "In a similar model with breast cancer, HSP27 was found to be responsible for vasculogenic mimicry activity in populations of mammosphere-forming CD24(−)CD44(+)ALDH(+) CSCs; the activity’s manifestation was mediated by the EGF-triggered signaling pathway, resulting in HSP27 phosphorylation." (PMID 32268506, 2020). "In the T47D breast cancer cell line, expression of PRB increased the CD44+/CD24Low/− subpopulation, and even though the number of tumorspheres did not vary between the T47D, YB, and YA cell lines, those generated from YB were bigger, more irregular and had increased clonogenic capacity." (PMID 32932770, 2020). "A study using the inflammatory breast cancer cell line SUM149, found that ALDEFLOUR+ cells comprised approximately 5% of the total cell population, and of this ALDEFLOUR+ population, 13% of cells were CD44+/CD24−, compared to only 3% in ALDEFLOUR- cells." (PMID 33003540, 2020). "We indicated that the CC50 value of andrographolide in BCSCs is significantly higher than that in non-BCSCs such as human CD24-/CD44- breast cancer cells and human MCF-7 breast cancer cells." (PMID 33211707, 2020). "Therefore, breast-cancer derived CTC cell lines expressing E/M hybrid phenotypes (cytokeratins 8/18, vimentin, CD44) have been shown to metastasize after tail-vein or intracardiac injection." (PMID 32575608, 2020). "In addition, pKAL inhibited expressions of the proteins (CD44, Oct 3/4, β-catenin and MMP-9) that are assumed to be related to the RT resistance of RT-R-MDA-MB-231 human breast cancer cells." (PMID 32326231, 2020). "In this study, we found that brain-tropic breast cancer cells have an enrichment in their stem-like profile, since they display increased MFE, form larger tumors when inoculated in the CAM, and show a higher percentage of the CD44+/CD24−/low population." (PMID 33182375, 2020). "In this study, we demonstrated that FOXO3a inhibited mammosphere formation ability, percentages of ALDH+ cells, subpopulation of CD44+/CD24− cells in vitro, and tumorigenicity in vivo, which supported an important role of FOXO3a in inhibiting CSC properties of breast cancer cells." (PMID 31296961, 2020). "Additionally, either deleting CD44 or inhibiting HA synthesis decreases inflammatory cytokine (e.g., CCL2) production by breast carcinoma cells." (PMID 32455980, 2020). "Cells with high CD44 but low CD24 expression (CD44high/CD24−/low) and high aldehyde dehydrogenase activity (ALDHbr) are widely considered to be drivers of metastasis, therapy resistance and tumor recurrence in breast cancer." (PMID 32423137, 2020). "We have previously demonstrated using Microarray analysis that CD44 promotes breast cancer cell invasions and metastasis to the liver 37, and identified CTTN 15 and BIRC5 37 as downstream target genes underpinning CD44-promoted cell survival, migration and invasion." (PMID 31929744, 2020). "Here, we report a CD44 and scavenger receptor class B1 dual-targeting hyaluronic acid nanoparticle (5K-HA-HPPS) loaded with the near-infra-red fluorescent dye DiR-BOA for SLN imaging in breast cancer." (PMID 33014359, 2020). "In addition, CD24, CD44, CD133, EpCAM, and ALDH1 have been documented as beneficial CSC markers in the chemically-induced rat mammary carcinoma model." (PMID 33375383, 2020). "Our results also confirmed a high expression of CD44 in BT-20 breast cancer cell line, while the CD44 expression was not detectable in the MCF-7 cell line." (PMID 32151062, 2020).